IL33 (interleukin 33)
Diseases named in the same sentence as IL33 in open-access papers (continued):
Sharing a sentence is not in itself a finding about the gene and the disease.
tumor (continued). "Mechanistically, IL-33 enhanced the sensitivity of CRC cells to 5-FU only in the presence of T cells, which led to the activation of both tumor cell-intrinsic apoptotic and immune killing-related signals, thereby synergizing with 5-FU to induce apoptosis of CRC cells." (PMID 37056569, 2023). "Notably, Ercolano G., found that blocking PPARγ in IL-33-dependent tumors such as CRC can greatly suppress the IL-33-stimulated release of type 2 cytokines from ILC2, thus decreasing tumor migration." (PMID 37686309, 2023). "Besides the combined in vitro action of IL-33 and SCF in shaping MC phenotype and functions, a previous finding supports the ability of SCF to favor MC infiltration and activation in the tumor microenvironment." (PMID 37730723, 2023). "Furthermore, IL33 expression levels were positively correlated with those of Th1 cytokines (IL2 and IFNG) and Th2 cytokines (IL4 and IL10) in 41 tumor tissues." (PMID 37056569, 2023). "FCGR3 was also expressed on the surface of cDC1s of in vitro-generated FL-33-DCs and in vivo splenic cDC1s of IL-33-injected mice, regardless of tumor-bearing condition, but was undetectable in any DC subsets of FL-DCs or FL-GM-DCs." (PMID 37246159, 2023). "As a result, GM-CSF-induced CD103+ cDC1s did not promote CD8+ T-cell priming capacity, so tumor growth was not inhibited or was even promoted, unlike with IL-33." (PMID 37246159, 2023). "The combination of IL-33 and immune checkpoint blockade(ICB) has a better anti-tumor effect." (PMID 37153553, 2023). "Another study induced chronic, tumor-promoting allergic contact dermatitis (ACD) in 6- to 8-week-old mice by treating them with 1-fluoro-2,4-dinitrobenzene (DNFB) and found that IL-33 expression was key in inducing the transition from acute, tumor-suppressing inflammation to chronic inflammation." (PMID 36945046, 2023). "As previously reported, tumor localization influences immune response, and CRC patient prognosis, and the expression of IL-33 increased in left-sided CRC patients in comparison with right-sided ones, reaching even higher levels in CRC with lymph node (LN) metastasis." (PMID 37296602, 2023). "Twelve days after ACT (upon tumor response), we observed significantly more total CD8+ TILs and marked intratumoral expansion of transferred OT1 cells following PD1d/IL-2v/IL-33 OT1 ACT, while PD1d/IL-2v OT1 or PD1d/IL-33 OT1 cells showed modest or minimal levels of tumor expansion, respectively." (PMID 37081150, 2023). "IL-33-mediated tumor suppression did not occur in Batf3−/− mice, indicating that conventional type 1 dendritic cells (cDC1s) play a key role in IL-33-mediated antitumor immunity." (PMID 37246159, 2023). "Tumor-specific cytotoxic T-cell (CTL) responses in the tumor were significantly enhanced in IL-33-OL-33 wild-type (WT) tumor-bearing (TB) mice but not in IL-33-treated Batf3−/− TB mice." (PMID 37246159, 2023). "In addition, authors found that FMRP‐KO significantly down‐regulates the expression of IL33, a factor is known to stimulate Treg production, while overexpression of IL33 in FMRP‐KO cancer cells promotes tumor growth in mice." (PMID 36968189, 2023). "Indeed, we have demonstrated previously that nuclear FAK induces the expression of proinflammatory cytokines and chemokines, including IL-33 and CCL5, which inhibit antitumour immunity and drive tumour growth in vivo." (PMID 36959177, 2023). "IL-33 can affect the barrier function of the intestine leading to increased translocation of bacterial products and inducing the production of pro-tumorigenic cytokines, such as IL-6, by immune cells that activate STAT3, thereby promoting tumor growth." (PMID 37296602, 2023). "By day 5, we observed >800-fold more CD8+ tumor-infiltrating lymphocytes (TILs) in tumors treated with PD1d/IL-2v/IL-33 OT1 relative to non-treated B16-OVA tumors." (PMID 37081150, 2023).
tumor (continued). "Furthermore, both IL-33 and IL-25 have been shown to promote angiogenesis which also contributes to metastasis, and genetic deletion of ST2 reduced VEGF expression and tumour burden in mouse breast cancer." (PMID 37455828, 2023). "In addition, tumor-derived IL-33 was shown to increase the number of CD103+ DCs in the tumor microenvironment and to reactivate the tumor-resident CD8+ T cells required for antitumor responses." (PMID 37246159, 2023). "It was recently reported that IL-33 activates tumoral ILC2s that double the abundance of intratumoral CD103+ DCs, priming and recruiting CD8+ T cells into orthotopic pancreatic tumors to restrict tumor growth in mice." (PMID 37246159, 2023). "IL-33-induced FcεRIa+ macrophages activate TGF-β signaling, which promotes tumor cell invasion." (PMID 37246159, 2023). "In the tumor tissue and serum of NSCLC patients, IL-33 levels were noticeably elevated." (PMID 36874133, 2023). "The oncogene Kras-G12D increases the expression of IL-33 in PDAC cells, and fungi in PDAC tissue can drive IL-33 secretion, further recruiting and activating Th2 cells and ILC2 in the tumor, ultimately inhibiting the antitumor immune response and promoting tumor progression." (PMID 37691931, 2023). "Overall, we preliminarily surmise that IL-33 may orchestrate an immune-activated TME by mediating a positive feedback loop between T cells and CRC cells, which cooperates with 5-FU to inhibit tumor progression." (PMID 37056569, 2023). "Moreover, IL-33 also promotes CCL5 production by eosinophils and CD8+ T cells that recruit NK cells to the tumor site." (PMID 38090567, 2023). "Various CAF-secreted solute factors, such as IL-6, IL-33, TGF-β, stromal cell derived factor-1 (SDF-1), and CAF-derived cardiotrophin-like cytokine factor 1 (CLCF1) produce tumor-promoting signals that mediate the signal transduction of tumor cells or other cells in the TME." (PMID 37217855, 2023). "Nevertheless, the increased population of CD8+ T cells observed in IL-33-treated Batf3−/− mice was not effective enough to suppress tumor growth in Batf3−/− TB mice, as previously reported." (PMID 37246159, 2023). "Interestingly, IL-33-mediated angiogenesis in this setting was thought to be VEGF independent, as tumour VEGF expression was lower in MC38-IL-33 tumours compared to control." (PMID 36263033, 2022). "Consistent with evidence suggesting that increased IL-33 levels promote antitumor T cell responses, PDA tumor growth was profoundly inhibited in the rIL-33 group compared with control conditions with concomitant and robust increases in CD8+ T cell infiltration." (PMID 36256464, 2022). "IL-33 expression in the tumor cytoplasm of patients with cervical cancer is positively correlated with infiltration of CD3+ T cells, CD8+ T cells, and PD-L1 expression in tumor tissues." (PMID 36291105, 2022). "Further studies indicated that IL-33 induces polarization of M2-like macrophages by activating ornithine decarboxylase, which helps form an immunosuppressive ESCC tumor microenvironment and promotes tumor progression." (PMID 35646112, 2022). "However, in B16 tumor-bearing mouse models, IL-33 promotes the infiltration of NK cells and CD8+ T cells and increases IFN-γ and perforin expression to kill tumor cells and inhibit tumor growth." (PMID 36291105, 2022). "Serum IL-33 concentration in tumor-bearing mice tended to be higher than that in tumor-free mice though not to a statistically significant degree." (PMID 35805039, 2022). "In murine PDAC, IL-33 activates TILC2s to secrete CCL5, which subsequently recruits CD103+ DCs to TME; DCs then activate CD8+ T cells through antigen presentation, thereby enhancing the anti-tumor immunity." (PMID 35720302, 2022). "A recent study established a role for ST2 in the recruitment of mast cells to gp130F/F tumours but did not directly examine IL33 itself." (PMID 35677533, 2022).
tumor (continued). "Indeed, blockage of IL-33 is known to prevent the growth of NSCLC by inhibiting M2 macrophage polarization and reducing the accumulation of Treg cells in the tumor microenvironment." (PMID 35354498, 2022). "IL-33 is able to promote the function of peripheral blood mononuclear cells (PBMCs), dendritic cells (DCs), CD8+ T cells and natural killer (NK) cells, which can in turn inhibit the tumor growth and metastasis." (PMID 35634336, 2022). "RNA-seq also revealed that IL33 transcript levels were significantly increased in all tumor samples regardless of the genotype." (PMID 35091681, 2022). "Therefore, the IL-33/ST2 axis exerts pro- and anti-tumorigenic effects depending on expression levels, tumor and cell types, and the microenvironment." (PMID 36291105, 2022). "On the other hand, genetic deficiency of IL-25 or rIL-25 treatment did not alter tumour Treg frequency in Apc1322T/+ mice, suggesting that tumour Tregs preferentially respond to IL-33 and not IL-25 in CRC." (PMID 36263033, 2022). "Furthermore, both IL-25 and IL-33 modulate pathways previously known to contribute to CRC tumorigenesis, including angiogenesis, tumour stemness, invasion and metastasis." (PMID 36263033, 2022). "In a separate model, through IL-33-mediated upregulation of COX-2 in tumour cells, IL-33 transgenic mice with subcutaneous implants of MC38 tumours showed increased growth and proliferation markers compared to wild type mice, which was abrogated upon treatment with a selective COX2 inhibitor." (PMID 36263033, 2022). "As we have shown in human CRC patients, high tumor IL25 expression is associated with poor CRC patient survival, whereas IL33 expression does not discriminate between better or worse prognosis." (PMID 35658010, 2022). "Although ILC2s were not investigated in mice administered with IL-33, tumor growth and metastasis were inhibited via eosinophil recruitment." (PMID 35844571, 2022). "Interleukin 33 (IL-33) increases CD8+ T-cell functionality and is contributed to its proliferation and infiltration of CD8+ T cells, thereby acting as a suppressor of tumor growth." (PMID 35432340, 2022). "Indeed, IL-33 expression correlated strongly with CD8A and granzyme B as well as genes like BATF3, IRF8, THBD, CLEC9, and XCR1 that are required for tumor antigen cross-presentation functionality of CD103+ dendritic cells (DCs)." (PMID 36256464, 2022). "Mice inoculated with IL-33-expressing tumor cell lines, including EL4, CT26, and B16F10, resulted in a substantial expansion of intertumoral ILC2, which inhibited tumor growth and induced apoptosis of tumor cells through the production of CXC chemokine receptor 2 ligands." (PMID 35844571, 2022). "This was mediated by a cytokine gradient from non-tumor to tumor tissue involving among others the cytokines IL-33, IL-4 and IL-1β." (PMID 35663967, 2022). "Compared with those in the WT mice, the average tumor weight (P < 0.05), volume (P < 0.05), and body weight (P < 0.05) in ST2−/− mice were lower, but the opposite effects were observed in the IL-33-overexpression group (P < 0.05)." (PMID 33628592, 2021). "Additionally, we found a strong correlation between IL‐33 secretion in the ESCC tissue samples and the tumour TNM stages." (PMID 33305406, 2021). "Eosinophils are activated by IL33, IFN-γ, and IL-5, and activated eosinophils secrete MBP, tumor necrosis factor (TNF)-α, eosinophil peroxidase, and granzyme B, which facilitate the killing of tumor cells." (PMID 35011007, 2021). "Furthermore, IL-33 induces TAM prostaglandin-2 secretion which enhances cancer stemness and tumor growth." (PMID 33783686, 2021).
tumor (continued). "The increased expression of the exhaustion markers PD-1, Eomes, and TOX on tumor-infiltrating CD8+ T cells in mice lacking intratumoral IL-33 production by skin-derived Cxcl13-Cre+ FSCs is consistent with the phenotype of terminally exhausted T cells." (PMID 34354077, 2021). "In addition, IL-33 has been shown to drive anti-tumour CTL and NK cell activity that reduces melanoma tumour growth and metastasis." (PMID 33401460, 2021). "Similarly, in the CT26 adenocarcinoma mouse model, administration of recombinant IL-33 (rIL-33) enhanced, while inhibition of IL-33 diminished, the expansion of ST2+ Treg cells in tumor tissue and spleen, resulting in tumor growth." (PMID 34209038, 2021). "Furthermore, it has been found that IL-33 promotes EMT and tumor progression by regulating the expression of CCL2 and recruiting Tregs through the TGF-β signaling pathway in ESCC." (PMID 33390169, 2021). "This study investigates the role of the IL-33/ST2 axis in TAMs, its effects on tumor growth, and whether it participates in the mutual conversion between the M1 and M2 phenotypes." (PMID 33628592, 2021). "Mice treated with C-87 exhibited lower concentrations of the following pro-inflammatory cytokines in the tumor paw compared to vehicle-treated tumor-bearing mice: TNFα (p < 0.05), NGF (P < 0.05), IL1β (P < 0.05), IL4 (P < 0.05), IL28β (P < 0.001), IL33 (P < 0.01), MIP3α (P < 0.01)." (PMID 33469141, 2021). "Furthermore, it is necessary to clarify how USP17 achieves specificity through substrate interactions in different tumor microenvironments because recent studies have shown that USP17 regulates the stability and nuclear function of IL-33." (PMID 34454495, 2021). "In mouse tumor models, particularly in the absence of an adaptive immune system, we reported that IL-33 promoted the expansion of active ILC2s via ST2 that facilitated tumor growth by diminishing NK cell activation and tumor-killing." (PMID 34209038, 2021). "On the contrary, we observed an IL‐33–induced immunosuppressive response in tumour‐bearing mice with no side effects." (PMID 33305406, 2021). "CAFs and tumor cells need reciprocal communication to stimulate mediators such as vimentin, matrix metalloproteinase (MMPs); periostin; Insulin growth factor-2 (IGF2); IL-33; and CXCL12, related to and tumor growth, invasion, and downregulation of tumor suppressor genes." (PMID 34204259, 2021). "Considering that IL-33 exerts its function by binding to its receptor ST2 on target cells, the expression of ST2 and sST2 or the ratio of ST2/sST2 will be a critical regulatory step for directing pro- and anti-tumor activity by IL-33." (PMID 34209038, 2021). "In ApcMin/+ mice, IL-33 derived from epithelial cells enhanced the proliferation of ST2+ Treg cells and induced Th2 cytokine milieu in the gut, which was correlated with increased tumor burden." (PMID 34209038, 2021). "However, the co-expression of IL-33 and CXCR4 showed a significant correlation with clinical parameters, including TNM stage, nodal involvement, stage, and tumor differentiation." (PMID 34298657, 2021). "IL-33 treatment also drove the induction and cytotoxic activities of DC-induced Tc9 cells, a subset of effector CD8+ T cells producing cytotoxic IL-9, and further promoted the therapeutic efficacy of DC-based tumor vaccines." (PMID 34209038, 2021). "When we identified differentially expressed genes in responder and nonresponder tumor cells, we found that IL-33 expression was noticeably lower in responder tumor cells." (PMID 34433873, 2021). "It is conceivable that the decrease in IL-33 determines on the one hand the progression from MGUS to MM and on the other hand weakens the immune response not only towards tumour cells but also towards exogenous antigens, thus contributing to the genesis of secondary immunodeficiency." (PMID 34445745, 2021).
tumor (continued). "Previous study also found that the median IL-33 mRNA expression levels varied significantly but multiple comparisons between each tumor grade did not demonstrate statistically significant results." (PMID 32003751, 2020). "Of note, as previously reported by others, IL-33 induced PD-1 expression on ILC2s, and combined administration of recombinant IL-33 and anti-PD-1 antibodies acted synergistically in sustaining ILC2 anti-tumor functions and in restoring CD8+ T-cell cytotoxicity." (PMID 33255582, 2020). "Dual therapy with recombinant IL-33 plus anti-PD-1 engaged ILC2s to accumulate in orthotopic KPC tumors and improved T cell infiltration through DC priming, allowing for improved mouse survival and decreased tumor volume." (PMID 33584701, 2020). "IL-33 enhances NK and CD8+ T cell function, thereby, inhibiting tumour growth in transgenic mice." (PMID 33308251, 2020). "Given that IL33 supports tumor growth, FLJ22447 is an important factor for OSCC cell proliferation, indicating that autophagy inhibition in CAFs is relevant for OSCC tumor growth." (PMID 33363032, 2020). "In fact, over time in the absence of nuclear IL-33 there is very little evidence of any tumor burden." (PMID 33020472, 2020). "Furthermore, the IFN-inducing DNA sensor STING promoted tumor cytotoxicity by stimulating some chemokines (CXCL10 and CCL5) and IL-33, which participated in NK cell infiltration and activation in a mouse model of NK-sensitive melanoma." (PMID 33329534, 2020). "For instance, IL-33 release in murine HCC showed to markedly inhibit tumor growth via activated CD4+ and CD8+ T cells, in IL-33-expressing tumor-bearing mice, while IL-18/IL-12 cytokine therapy was effective in tumor regression prompted by induction of NK cells." (PMID 32899197, 2020). "Higher IL-33 expression was significantly correlated with Hepatitis B virus positivity (χ2 = 4.896; P = 0.027) but not with sex, tumour size, TNM stage, or differentiation." (PMID 33308251, 2020). "Regardless of the tumor type or tumor site, Ly6c1high CAFs (iCAFs) showed enrichment for Il33, Il6, Ccl7, Cxcl1 and Cxcl12 whereas α-SMAhigh CAFs (myCAFs) expressed high levels of Tgfb1, Tgfb2 and Ctgf." (PMID 32455670, 2020). "Interestingly, in the same study, the anti-tumor effect of IL-33 was potentiated after the depletion of ILC2, indicating a tumorigenic effect of this cell population in the presence of IL-33." (PMID 33371444, 2020). "IL-33 was shown to activate tumor ILC2s and CD8+ T cells in orthotopic pancreatic (but not heterotopic skin) tumors to impair pancreas-specific tumor growth." (PMID 33233582, 2020). "Similar outcomes have been shown in which IL-33, as a potent molecular adjuvant, can augment protective antiviral CD8+ T cell responses induced by a vaccine and boost DNA vaccine-induced protective anti-tumor T cell responses." (PMID 32315596, 2020). "A comprehensive analysis of cytokine profiles activated by IL-33 in various cancers may help clarify the CD4+ T cell subsets (including Treg) targeted by IL-33 in relation to the specific TME and anti-tumor response elicited." (PMID 33329534, 2020). "We also found a higher number of Tregs in tumors of ∆dblGATA-1 mice after IL-33 treatment vs. control with no change in tumor burden, suggesting that the increase in Tregs occurred independently of the presence of eosinophils." (PMID 32923137, 2020). "Recently, the IL-33/ST2L axis has been shown to be involved in the progression of cancer, either positively or negatively, depending on the cancer type, through modulating the tumor microenvironment, such as infiltration of T cells and inflammation." (PMID 32340025, 2020). "Gastric CAFs express high level of IL-33, while GC cells express ST2L, which suggest that IL-33/ST2L axis may act as an important mediator of tumor-stromal cell interactions in GC." (PMID 31659258, 2020).